LRP1 (LDL receptor related protein 1)
Diseases named in the same sentence as LRP1 in open-access papers (continued):
Sharing a sentence is not in itself a finding about the gene and the disease.
Sepsis (4 papers, 2014 to 2025). Sepsis is defined as life-threatening organ dysfunction caused by a dysregulated host response to infection. "A2MG-E microparticles also enhanced survival in murine sepsis, an action lost in mice transfected with siRNA for LRP1, a putative A2MG receptor." (PMID 24357647, 2014). "These vesicles are termed microparticles and one of their key components to prevent sepsis is A2MG, which acts through LRP1." (PMID 26031516, 2015). "In the present study we found that LRP1 was expressed on both human and mouse neutrophils and mediated the protective actions exerted by A2MG-E microparticles in murine sepsis." (PMID 24357647, 2014).
subarachnoid hemorrhage (4 papers, 2019 to 2022). A serious neurological disorder characterized by intracranial hemorrhage into the subarachnoid space. "Another study has shown that activation of LRP1 with COG1410 promotes microglial M1 to M2 phenotypic shift, and LRP1 was expressed in M2 phenotypes but not in M1 phenotypes of activated microglia in subarachnoid hemorrhage (SAH) mice." (PMID 36035210, 2022).
aneurysmal disease (3 papers, 2021 to 2023). "Further research should carefully address Tβ4 fluctuations within distinct cells of the medial layer and inflammatory infiltrate to determine causal versus consequential changes in relation to LRP1-regulated signaling and progression of aneurysmal disease." (PMID 33784254, 2021). "Smooth muscle-specific Lrp1 deletion, whether constitutively or inducibly targeted, strongly predisposes mice to develop atherosclerotic and aneurysmal disease." (PMID 37724952, 2023).
arterial diseases (3 papers, 2021 to 2024). "Consequently, LRP1 is implicated in various arterial diseases." (PMID 37724952, 2023). "LRP1 variants have been implicated by genome-wide association studies with risk of AAA and other arterial diseases." (PMID 33784254, 2021). "This may infer that Tβ4 levels are upregulated in synthetic VSMC populations to compensate for the dysregulated LRP1 function that is suggested from GWAS to occur in arterial disease." (PMID 33784254, 2021).
asthma (3 papers, 2020 to 2025). "Immunohistochemical results of lung tissues further verified the increased expression of LRP1 in ASM cells of mice with OVA-induced asthma." (PMID 40338656, 2025). "Ex vivo tracheal tension measurement experiments indicated that the tracheal contractile response to carbachol was significantly reduced after application of Lrp1 shRNA compared with NC shRNA in mice with OVA-induced asthma." (PMID 40338656, 2025). "LRP1-ICD overexpression inhibited full-length LRP1 protein levels by promoting its protein degradation rather than by suppressing its transcription, thus preventing further exacerbation of asthma." (PMID 40338656, 2025). "Overall, our results elucidated the mechanism underlying the role of LRP1 in ASM cell proliferation and provided a target for the clinical treatment of airway remodeling in asthma." (PMID 40338656, 2025). "Our results showed that the expression of full-length LRP1 was significantly elevated in the tracheal tissues of mice with OVA-induced asthma as evidenced by both Lrp1 mRNA levels and LRP1 β chain protein levels being increased." (PMID 40338656, 2025). "The Lrp1 mRNA and LRP1 protein levels in the tracheal tissues of mice modeling asthma were significantly higher than those in control mice." (PMID 40338656, 2025). "To explore the differential expression of LRP1 in airway tissues in asthma, we established an OVA-induced mouse model of chronic asthma." (PMID 40338656, 2025). "Immunohistochemistry results similarly indicated that the expression level of LRP1 in ASM cells of mice with OVA-induced asthma treated with Lrp1 shRNA was significantly lower than that in the mice treated with NC shRNA." (PMID 40338656, 2025). "For instance, LRP1 (asthma-related gene) is mainly expressed on neutrophils in the blood, but mainly expressed on macrophages and fibroblasts in the bladder." (PMID 39009607, 2024). "Elevated LRP1-ICD may negatively regulate LRP1, thus preventing further worsening of asthma because of excessive upregulation of LRP1." (PMID 40338656, 2025). "The transcriptional activation of Mt1-mmp enhanced the production of LRP1-ICD, which may promote protein degradation of the LRP1 via the lysosomal pathway, thereby preventing further exacerbation of asthma." (PMID 40338656, 2025). "This discrepancy may be attributed to the activation of LRP1 proteolytic processing during asthma, which would lead to the generation of more ICD fragments." (PMID 40338656, 2025). "In light of this finding, we hypothesize that the abnormal elevation of LRP1-ICD in the mouse asthma model may represent a protective mechanism, helping to prevent further exacerbation of asthma caused by excessive increases in full-length LRP1." (PMID 40338656, 2025). "Meanwhile, our study found that the increased LRP1 in the ASM of mice with OVA-induced asthma may activate the transcription of Mt1-mmp, thereby promoting the proteolytic process of LRP1 and generating more LRP1-ICD." (PMID 40338656, 2025). "Therefore, we hypothesized that ASM cells may be the primary cells in which LRP1 exerts its role in the pathogenesis of asthma." (PMID 40338656, 2025). "Hence, LRP1 holds promise as a therapeutic target for ASM remodeling in asthma." (PMID 40338656, 2025). "Targeted inhibition of full-length LRP1 using a specific shRNA in OVA-treated mice effectively alleviated ASM remodeling, suggesting that the increase in full-length LRP1 exacerbates asthma." (PMID 40338656, 2025). "However, the role of LRP1 in asthma airway remodeling remains unclear." (PMID 40338656, 2025). "(f) Inhibition of LRP1 significantly alleviated peribronchial inflammation, airway hyperreactivity, and ASM proliferation in mice with OVA-induced asthma, as well as suppressed OVA-induced increases in FGF2 and phosphorylated ERK expression." (PMID 40338656, 2025).
asthma (continued). "The α-SMA–stained area in the bronchial wall was significantly increased in mice with OVA-induced asthma compared with control mice and was significantly decreased in OVA-challenged mice after application of Lrp1 shRNA compared with NC shRNA." (PMID 40338656, 2025). "In conclusion, this study clarifies the molecular biological mechanism by which LRP1 regulates ASM proliferation, suggesting targeting full-length LRP1 as a strategy for therapeutic intervention in asthma airway remodeling." (PMID 40338656, 2025). "This study reveals how LRP1 regulates airway smooth muscle proliferation, offering a novel potential target for preventing and treating airway remodeling in asthma." (PMID 40338656, 2025). "Furthermore, we found that Lrp1 knockdown significantly reduced the levels of FGF2 and phosphorylated ERK compared with NC shRNA treatment in the tracheal tissues of mice with OVA-induced asthma, consistent with our in vitro findings." (PMID 40338656, 2025). "However, the role of LRP1, especially LRP1-ICD, in asthma airway remodeling has not been investigated." (PMID 40338656, 2025).
bladder urothelial carcinoma (3 papers, 2017 to 2022). "LRP1 is highly expressed in multiple types of cancers, and its mRNA level was associated with patient survival in bladder urothelial carcinoma." (PMID 35628341, 2022). "The correlation between LRP1 mRNA expression and patient survival was observed in bladder urothelial carcinoma." (PMID 33816497, 2021). "Although we examined the effects of LRP1 mRNA expression on survival in all ten malignancies, LRP1 mRNA expression demonstrated a significant correlation with patient survival only in urothelial carcinoma of the bladder." (PMID 29088295, 2017).
chronic obstructive pulmonary disease (3 papers, 2022 to 2026). A chronic and progressive lung disorder characterized by the loss of elasticity of the bronchial tree and the air sacs, destruction of the air sacs wall, thickening of the bronchial wall, and mucous accumulation in the bronchial tree. "Genome-wide association study has linked SNPs in LRP1 with several diseases, such as abdominal aortic aneurysm, hyperlipidemia, and chronic obstructive pulmonary disease (COPD)." (PMID 35202607, 2022). "Genetic variants in LRP1 are associated with chronic obstructive pulmonary disease (COPD), but the underlying mechanisms are unknown." (PMID 41999979, 2026). "We found that bronchial epithelium of patients with chronic obstructive pulmonary disease and airway epithelium of mice exposed to smoke had increased LRP1 expression." (PMID 35202607, 2022).
endometriosis (3 papers, 2022 to 2026). The growth of functional endometrial tissue in anatomic sites outside the uterine body. "Pid1, Saa3, Apoe, and Lrp1 were key DEGs in the monocyte-derived LpM population, and qPCR analysis also confirmed an upregulation of these genes in Tim4− peritoneal macrophages isolated from mice with induced endometriosis compared to those without (Saa3, Lrp1,P < 0.01)." (PMID 39255000, 2024).
esophageal cancer (3 papers, 2021 to 2023). A primary or metastatic malignant neoplasm involving the esophagus. "Mechanistically, we found that mAb-2E3 was able to bind the active form of PAI-1, inhibit metastasis of esophageal cancer in an LRP1-dependent manner, and block the binding between LRP1-Cluster II and PAI-1." (PMID 36605486, 2023). "Studies have shown that tumor fibroblast-derived PAI-1 in esophageal cancer can induce AKT and ERK1/2 signaling pathways through LRP1 and promote cell metastasis 23,52." (PMID 36605486, 2023).
experimental autoimmune encephalomyelitis (3 papers, 2016 to 2019). An autoimmune demyelinating disease of the central nervous system that is produced experimentally in animals by the injection of homogenized brain or spinal cord in Freund's adjuvant. "Moreover, deletion of Lrp1 in microglia worsens the course of experimental autoimmune encephalomyelitis and has been proposed to promote a proinflammatory milieu associated with disease exacerbation." (PMID 29251594, 2017). "Because we observed increased expression of LRP1 in the CNS during an animal model of MS, experimental autoimmune encephalomyelitis (EAE), we decided to probe the potential function of LRP1 during the human disease." (PMID 27400748, 2016). "Because inhibition of NF-kB is known to offer protection during experimental autoimmune encephalomyelitis (EAE), a mouse model of MS, placement of LRP1 at the crossroads of inflammation and phagocytosis raises the possibility of its involvement as a central regulator of MS pathology." (PMID 27400748, 2016).
fibrosarcoma (3 papers, 2010 to 2013). A malignant mesenchymal fibroblastic neoplasm affecting the soft tissue and bone. "In HT1080 fibrosarcoma cells, Webb and colleagues demonstrated that LRP-1 deficiency led to increased phosphorylated ERK level that stimulates cell migration and invasion." (PMID 20644732, 2010). "Concomitant activation of RTKs and LRP1 leads to sustained activation of ERK1/2 in fibrosarcoma cells." (PMID 24086544, 2013). "By binding to LRP1, PAI-1 also enhanced the migration of rat and human smooth-muscle cells, mouse embryonic fibroblast-1, and fibrosarcoma cells (HT1080)." (PMID 22747686, 2012).
glaucoma (3 papers, 2012 to 2025). Increased pressure in the eyeball due to obstruction of the outflow of aqueous humor. "Similarly, there is little known about modulation of LRP1 activity (endocytosis, signaling) in glaucoma." (PMID 35693935, 2022). "However, the disruption of focal adhesion connections to actin-containing stress fibers suggests that TSP-1/Calr/LRP1 signaling would decrease cellular contractility and be protective against glaucoma." (PMID 35693935, 2022). "Little is known about regulation of the TSP-1 co-receptors, Calr and LRP1, in glaucoma." (PMID 35693935, 2022). "Despite the focus on TSP-1 as a regulator of TGF-β activation in glaucoma, in contrast, the possible functions of the TSP-1/Calr/LRP1 complex in glaucoma remain unexplored and unknown." (PMID 35693935, 2022).
HIV-1 infection (3 papers, 2012 to 2023). The type species of lentivirus and the etiologic agent of acquired immunodeficiency syndrome (AIDS). "Given that none of the surface expression of these receptors were upregulated by HIV-1 infection in MDMs, we focused on receptors of phosphatidylserine-binding ligands, such as CD91/LRP-1." (PMID 22412921, 2012). "This indicates that productive HIV-1 infection is required to modulate surface expression of the scavenger receptor CD91/LRP-1 in MDMs." (PMID 22412921, 2012). "Interestingly, MDMs treated with either Furin inhibitor I, or neutralizing anti-TGF-β antibodies, at the time and following HIV-1 infection expressed significantly less surface CD91/LRP-1 as compared to untreated cells." (PMID 22412921, 2012). "Furthermore, we show for the first time that HIV-1 infection increases surface expression of phosphatidylserine receptor CD91/LRP-1 on human macrophages, thereby leading to a Leishmania uptake by uninfected bystander cells in HIV-1-infected macrophage populations." (PMID 22412921, 2012). "Our findings that surface CD91/LRP-1 is increased in MDMs treated with Tat, as well as following HIV-1 infection, suggested, at first, that this entry pathway is involved in enhanced amastigote uptake by macrophages." (PMID 22412921, 2012). "MDMs treated prior and during HIV-1 infection with the viral entry inhibitor Maraviroc (MVC), a CCR5 antagonist, or EFZ had similar levels of surface CD91/LRP-1 as compared to uninfected MDMs." (PMID 22412921, 2012). "Even though uninfected bystander MDMs in HIV-1 infection account for Leishmania enhanced entry (not the macrophages productively infected with HIV-1), it is possible that both macrophage subpopulations may express higher levels of surface CD91/LRP-1." (PMID 22412921, 2012).
ischemic cardiomyopathy (3 papers, 2012 to 2026). Ischemic cardiomyopathy is a cardiomyopathy in which a weakness in the muscle of the heart due to inadequate oxygen delivery to the myocardium with coronary artery disease being the most common cause. "LRP1 was also strongly up-regulated in the myocardial tissue in the animal models of ischemia-reperfusion, as well as in patients with ischemic cardiomyopathy, supporting a role for LRP1 in IRI." (PMID 30696029, 2019). "Taken together, our results consistently point out that LRP1 is a potential molecular target to prevent myocardial CE accumulation, and thus the cardiac alterations induced by cholesterol loading in ischemic cardiomyopathy." (PMID 22873206, 2012). "Taken together, our results demonstrate for the first time that myocardial LRP1 expression and cholesteryl ester content appear strongly increased and interrelated in the myocardium of ischemic cardiomyopathy patients." (PMID 22873206, 2012). "Results from the present study show that there is a strong LRP1 upregulation that significantly correlates with cholesteryl ester accumulation in ischemic cardiomyopathy patients." (PMID 22873206, 2012). "However, further studies are required to know the precise role of HIF-1α on myocardial LRP1 overexpression in ischemic cardiomyopathy." (PMID 22873206, 2012). "The hub genes, including STAT3, MDM2, LRP1, IRS2, PRKCD, CCND2, and CISH, were validated to be highly expressed in adipocytes in ischemic cardiomyopathy patients with end-stage heart failure." (PMID 41869532, 2026). "Taken together, our results suggest that LRP1 upregulation is key for myocardial cholesterol ester accumulation in ischemic human hearts and that LRP1 may be a target to prevent the deleterious effects of myocardial cholesterol accumulation in ischemic cardiomyopathy." (PMID 22873206, 2012).
Liver cirrhosis (3 papers, 2012 to 2023). "Liver cirrhosis is associated with decreased expression of LRP1." (PMID 27644406, 2016). "However, other clinical characteristics, including age, sex, preoperative serum α-fetoprotein (AFP), liver cirrhosis, Child–Pugh score, preoperative treatment, tumor number and differentiation were not significantly related to the expression of LRP1." (PMID 22427881, 2012).
liver diseases (3 papers, 2021 to 2023). "Low hepatic expression of LRP1 is observed in patients with liver diseases, accompanied with high levels of circulating Aβ, suggesting impaired LRP1-mediated clearance of Aβ." (PMID 37377968, 2023). "Hepatic LRP1 inactivation also synergizes with dietary cholesterol to accelerate liver disease progression to steatohepatitis." (PMID 33500241, 2021). "In patients with liver diseases, low hepatic expression of LRP1 and high levels of circulating Aβ are observed because Aβ clearance decreases due to low hepatic LRP1 activity." (PMID 33867971, 2021). "Thus, we posit that hepatic LDL receptor-mediated lipoprotein uptake and degradation pathway is responsible for the protection against HFHC diet-induced liver disease in LRP1 NPxY mutant mice." (PMID 33500241, 2021).
lung disease (3 papers, 2021 to 2022). "Therefore, LRP1 deficiency leads to greater lung inflammation and damage and exacerbates smoke-induced lung disease." (PMID 35202607, 2022). "Although originally described as a lipoprotein receptor, LRP1 has subsequently been shown to affect a number of processes that are likely related to the development of inflammation and pulmonary disease." (PMID 35202607, 2022). "Airway epithelial club cell knockout of Lrp1 in mice influences lung inflammation and tissue damage and exacerbates smoke-induced lung disease due to a dysregulation of ROS and antioxidants." (PMID 36624735, 2022). "The link between TIMP2 and LRP1 could be relevant to pulmonary diseases." (PMID 36624735, 2022). "The underlined differentially expressed proteins were further evaluated by literature search and the LRP1 and S100A8 were found to be closely correlated with lung diseases and/or glucocorticoids." (PMID 34104089, 2021).
malaria (3 papers, 2014 to 2021). Malaria is a serious and sometimes fatal disease caused by a parasite that commonly infects a certain type of mosquito which feeds on humans. "Among the malaria pathways, we found that low-density lipoprotein receptor-related protein 1 (LRP1) was significantly changed when shrimp suffered from salinity stress." (PMID 26147449, 2015).
migraine headache (3 papers, 2018 to 2020). "It is worth noting that many nearby supporting SNPs for the LRP1 region were located in the nearby gene of STAT6 (which was also strongly associated with headache)." (PMID 29397368, 2018). "Genetic evidence also indicates LRP1 is a susceptibility factor for migraine headache." (PMID 31026304, 2019). "A number of protein similarities are observed with Panel I including LRP1, a marker for migraine headache, and PCLO a possible marker for depression." (PMID 31026304, 2019). "It is also interesting to note that the STAT6 gene was the most significant in the gene analysis with headache and not the LRP1 gene where the top SNP resides." (PMID 29397368, 2018). "In addition, a migraine headache pathway of related proteins also appears in this comparison, most notably ITGB3, KCNK18, NOTCH4, and LRP1 which could be interacting with glutamate receptors." (PMID 31026304, 2019).
sarcoma (3 papers, 2014 to 2023). A usually aggressive malignant neoplasm of the soft tissue or bone. "None of the 240 other sarcomas was positive for LRP1-SNRNP25 or KCNMB4-CCND3 fusions, nor for the four other fusion genes found in our analysis." (PMID 25300797, 2014).
skin cancer (3 papers, 2020 to 2022). "LRP2 can increase the proliferation of neural precursor cells in the subependymal zone and the proliferation and survival of skin cancer cells, however, it is unclear whether cells of the OL lineage express LRP2, or whether Lrp1 deletion could alter LRP2 expression." (PMID 33282858, 2020).